TNFSF10 (TNF superfamily member 10)
Diseases named in the same sentence as TNFSF10 in open-access papers (continued):
Sharing a sentence is not in itself a finding about the gene and the disease.
pancreatic adenocarcinoma (8 papers, 2003 to 2023). "Our study is the first to confirm that TNFSF10 is a prognostic risk gene for pancreatic adenocarcinoma." (PMID 37370756, 2023). "Compared with normal tissues, the expression levels of MET, DYNLL2, CDK1, TNFSF10, PIP5K1C, MSLN, and GKN1 were significantly increased in pancreatic adenocarcinoma cells (p < 0.05)." (PMID 37370756, 2023). "We identified seven prognostic genes (MET, DYNLL2, CDK1, TNFSF10, PIP5K1C, MSLN, GKN1) and validated that their related proteins, such as EGFR and MMP2, have a significant impact on the prognosis of pancreatic adenocarcinoma." (PMID 37370756, 2023). "At present, there is no article about the relationship between the TNFSF10 gene and the prognosis of pancreatic adenocarcinoma." (PMID 37370756, 2023).
psoriasis (8 papers, 2010 to 2022). An autoimmune condition characterized by red, well-delineated plaques with silvery scales that are usually on the extensor surfaces and scalp. "The list of the DEG in common in the 4 studies contains many genes known to be upregulated in psoriasis, such as IFNγ-regulated genes STAT-1, STAT-3 and MX1; antimicrobial peptides (beta defensin 4, lipocalin 2, S100A7); and pro-inflammatory proteins such as IL-8, CXCL1, IL-1F9, TNFSF10/TRAIL." (PMID 20422035, 2010).
dengue (7 papers, 2012 to 2025). "Serum from patients with dengue had significantly increased TNFSF10 protein levels." (PMID 26302899, 2015). "The increased expression of TNFSF10 and CXCL8 in our patient cohort can be correlated clinically to lymphocyte and neutrophil counts in dengue HVR patients." (PMID 37644081, 2023). "When comparing controlled versus hemorrhagic dengue (GSE18090, unpublished data), we found that the individual expression of ISG15, OASL, OAS2 and TNFSF10 can be used to anticipate the complication status of dengue infection into a hemorrhagic outcome." (PMID 26302899, 2015).
HCMV infection (7 papers, 2013 to 2024). "Other anti-viral candidates not described yet in the context of HCMV infection include the broadly anti-viral ISG15 interactor RNF21341 and TNFSF10, which encodes the NK cell-activating protein TRAIL42,43." (PMID 38409141, 2024).
oral cancer (7 papers, 2007 to 2020). "In oral cancer cells, cathepsin B has been shown to mediate TNFSF10-induced apoptosis." (PMID 25050621, 2014).
ischemia (6 papers, 2014 to 2025). A hypoperfusion of the BLOOD through an organ or tissue caused by a PATHOLOGIC CONSTRICTION or obstruction of its BLOOD VESSELS, or an absence of BLOOD CIRCULATION. "TNFSF10 is a more classic inducer of neuronal apoptosis whose action has been demonstrated in vitro and in vivo following auto immune neuro-inflammation, ischemia and HIV infection." (PMID 34835061, 2021).
lymphopenia (6 papers, 2017 to 2022). Reduction in the number of lymphocytes. "TNFSF10, induces apoptosis of CD4 + and CD8 + T cells and is upregulated, which might explain the cause of lymphopenia in the process of ASFV infection." (PMID 34412678, 2021). "It was reported that FASLG and TNFSF10 can trigger apoptosis in both CD4+ and CD8+ T cells, which could explain the lymphopenia during ASF infection." (PMID 31725732, 2019).
non-Hodgkin lymphoma (6 papers, 2013 to 2022). Distinct from Hodgkin lymphoma both morphologically and biologically, non-Hodgkin lymphoma (NHL) is characterized by the absence of Reed-Sternberg cells, can occur at any age, and usually presents as a localized or generalized lymphadenopathy associated with fever and weight loss. "TNFSF10 was found to be involved in promoting tumor proliferation in non-Hodgkin’s lymphoma by activating the NF-κB pathway." (PMID 34079795, 2021). "TNFSF10 has been shown to enhance tumor progression in non-Hodgkin lymphoma by activating NF-κB in apoptosis-resistant cells." (PMID 33276546, 2020).
prostate adenocarcinoma (6 papers, 2006 to 2019). "Therefore, we determined the top 50 genes co-expressed with TNFSF10 in PCa tissue (TCGA dataset, Prostate Adenocarcinoma, PanCancer Atlas)." (PMID 31828111, 2019).
cutaneous melanoma (5 papers, 2018 to 2024). A primary melanoma arising from atypical melanocytes in the skin. "In cutaneous melanoma, TNFSF10 is closely associated with autophagy and immune cell infiltration, with low expression being linked to poorer clinical outcomes." (PMID 39660984, 2024).
Immunodeficiency (5 papers, 2009 to 2019). Failure of the immune system to protect the body adequately from infection, due to the absence or insufficiency of some component process or substance. "DEGs that enriched to “immune system diseases” played critical roles in cell-matrix communication (THY1, LVRN, LUM, TIMP3, SPOCK1, LGALS3BP, FAT2, and SERPINE2) as well as inflammation (IL1R2, CD22, PTGES, TNFSF10, IL2RB, C3, SERPING1, and IL-17RE)." (PMID 30131724, 2018).
inflammatory bowel disease (5 papers, 2011 to 2024). A spectrum of small and large bowel inflammatory diseases of unknown etiology. "TNFSF10 a proapoptotic member of the tumor necrosis factor family, has been shown to be highly up-regulated in patients with inflammatory bowel disease and neurodegenerative diseases." (PMID 38742104, 2024).
malaria (5 papers, 2013 to 2024). Malaria is a serious and sometimes fatal disease caused by a parasite that commonly infects a certain type of mosquito which feeds on humans. "A peculiar response to malaria and vaccination was found for Tnfsf10 encoding TRAIL, which is currently considered as specifically expressed by lrNK cells." (PMID 33202767, 2020).
osteoarthritis (5 papers, 2020 to 2026). A noninflammatory degenerative joint disease occurring chiefly in older persons, characterized by degeneration of the articular cartilage, hypertrophy of bone at the margins and changes in the synovial membrane. "LncRNA TNFSF10 was validated as a novel potential biomarker for osteoarthritis progression." (PMID 37779916, 2023). "Liu and colleagues proposed that TNFSF10 overexpression probably stimulated proliferation and inflammation and inhibited apoptosis by regulating the miR-376-3p/FGFR1 axis in osteoarthritis." (PMID 35151359, 2022). "LncRNA TNFSF10 impacted the miR-376–3p/FGFR1 pathway and led to osteoarthritis progression." (PMID 37779916, 2023).
periodontitis (5 papers, 2013 to 2021). An acute or chronic inflammatory process that affects the tissues that surround and support the teeth. "In conclusion, P. gingivalis HmuY protein might contribute to the survival of PBMC in periodontitis by regulating the transcriptional profile of genes involved in apoptosis, such as FASL, caspase 9, APAF1, FAS, TNFSF10 (TRAIL), and BAK1." (PMID 31011284, 2019).
skin tumors (5 papers, 2016 to 2025). "Conversely, NK inactivation genes including Itga1 (Cd49a), Inpp4b, Tnfsf10, Il7r, and Cxcr6 dramatically decreased in skin tumors." (PMID 40282557, 2025).
ZIKV infection (5 papers, 2018 to 2025). "Top selected ZIKV infection-associated genes from RPE cells are shown in a heatmap that includes multiple immune response genes, such as CCL5, CXCL11, CXCL1, IFNB1, IL6 and TNFSF10." (PMID 30046058, 2018). "Several genes involved in cell death (CASP1, TNFSF10, RIPK2, and BID) were also activated upon ZIKV infection." (PMID 30781519, 2019).
avian influenza (4 papers, 2009 to 2018). Infection of domestic and wild fowl and other birds with influenza A virus. "However, expression of TNFSF10 and TNFRSF10a genes was significantly higher in cells transfected with PB1-F2 of highly pathogenic avian influenza-H5N1-WB virus." (PMID 30687405, 2018).
infertile (4 papers, 2020 to 2025). "Our RT-qPCR analysis also showed that TNFSF10 expression was increased in luteinized GCs from women with PCOS-related infertility compared with those without PCOS, although the difference was not statistically significant." (PMID 40083347, 2025).
mild cognitive impairment (4 papers, 2017 to 2025). "In conclusion, TNFSF10 orchestrates sustained central and peripheral immune responses that substantially contribute to the progression of brain pathology along with cognitive impairment in the 3xTg-AD mouse model." (PMID 39918606, 2025).
myocarditis (4 papers, 2023 to 2025). Myocarditis is a condition that is characterized by inflammation of the heart muscle (myocardium). "TNFSF10 (TRAIL) is a cytokine that plays a role in the regulation of apoptosis, and elevated TNFSF10 is associated with a favorable prognosis in myocarditis, which is also consistent with findings in cardiovascular disease." (PMID 40906170, 2025).
prostate (4 papers, 2013 to 2021). "Overexpression of TNFSF10 could ameliorate EMT induced by hypoxia in proximal tubules, suggesting the potential therapeutic effect of miR-545-3p–TNFSF10 in hypoxia-related kidney injury." (PMID 34356656, 2021).
eosinophilia (3 papers, 2022 to 2023). "A TNFSF10 knock out mouse‐model has been found to have reduced airway hyperactivity, peribronchial eosinophilia, and levels of mast cells in the airways compared with wild‐type mice." (PMID 34813682, 2022).
invasive breast carcinoma (3 papers, 2011 to 2021). A carcinoma that infiltrates the breast parenchyma. "Besides, TNFSF10 polymorphism has been identified as a possible prognostic factor for survival in patients undergoing surgery for invasive breast cancer.These encouraging studies hint at the potential of TNF family members in their efforts to diagnose and predict cancer." (PMID 34630563, 2021).
lymph node metastasis (3 papers, 2020 to 2023). "Only TNFSF10 had a significant positive relationship with lymph node metastasis and staging, and patients with high TNFSF10 levels exhibited poor prognosis." (PMID 34167551, 2021). "Lymph node metastases are also associated with TNFSF10 expression, TNFSF10 expression was higher in N0 stages (without lymph node metastases)." (PMID 37670976, 2023). "Additionally, TNFSF10's expression was lower in CD4+ T cells, CD8+ T cells and fibroblasts of SKCM with lymph node metastasis." (PMID 37670976, 2023).
Salmonella Infections (3 papers, 2013 to 2022). Infections with bacteria of the genus SALMONELLA. "On the other hand, FOXO signaling (TNFSF10, PRKAB1, GADD45B, STK4, STAT3), Salmonella infection (ARPC2, ARPC5L, CCL3L3, CCL4) and lysosome (LAPTM4B, HGSNAT, CD164, ATP6V0A2) pathways were up-regulated, albeit weakly, in the HLA-DR- Teff subset." (PMID 30231065, 2018).
acne (2 papers, 2017 to 2023). An inflammatory process of the sebaceous glands which is characterized by comedones, nodules, papules and/or pustules on the skin.
graft versus host disease (2 papers, 2009 to 2019). An immune system disorder that occurs after allogeneic hematopoietic stem cell transplant and is a reaction of donor immune cells against host tissues. "TNFSF10 produced by macrophages is known to intervene in immune processes, such as graft-versus-host disease (GVHD), protection of privileged barriers, and others." (PMID 31409354, 2019).
Granuloma (2 papers, 2014 to 2020). A compact, organized collection of mature mononuclear phagocytes, which may be but is not necessarily accompanied by accessory features such as necrosis. "In addition, the expression of HESX1 and TNFSF10 genes was greater in C. burnetii-induced granulomas than in BCG-induced granulomas." (PMID 25566510, 2014). "It is noteworthy that in patients who did not form granulomas (n = 3), the expression of M1, M2, and granulomatous genes was markedly depressed, with the exception of TNFSF10." (PMID 32411623, 2020). "TNFSF10 was the only M1 gene markedly upregulated in patients who did not form granulomas." (PMID 32411623, 2020).
migraine (2 papers, 2017 to 2024). "Tnfsf10 is increased by excitotoxic spinal cord injury, downregulated in inflamed tissue, and associated with migraine susceptibility." (PMID 29422837, 2017).
rheumatic diseases (2 papers, 2015 to 2022). "Some of those significant DEGs above such as HLA-DRB5 and TNFSF10 have been proved to be key players in the pathogeneses of many autoimmune or rheumatic diseases." (PMID 35309355, 2022). "Previous studies have identified abnormal changes in TNFSF10 (TRAIL) among patients with distinct autoimmune and rheumatic diseases such as SLE." (PMID 35309355, 2022). "We identified a total of eight differentially expressed genes (TNFSF10, CX3CR1, LY96, TLR5, TXN, TIA1, PRKCH, PRF1), each associated with at least 3 of the 4 studied rheumatic diseases." (PMID 26352601, 2015). "By jointly analyzing 6 published microarray gene expression datasets about RA, SLE, OA and AS, we identified eight genes (TNFSF10, CX3CR1, LY96, TLR5, TXN, TIA1, PRKCH, PRF1) presenting general importance to rheumatic diseases." (PMID 26352601, 2015). "However, the roles of TNFSF10 high/+ monocytes in common autoimmune and rheumatic diseases have not been clearly defined." (PMID 35309355, 2022).
schizophrenia (2 papers, 2016 to 2021). A major psychotic disorder characterized by abnormalities in the perception or expression of reality. "Amongst the lowest p-values were 2 genes that might be of theoretical interest: CACNA2D3, directly involved in regulating the intracerebral calcium homeostasis, and TNFSF10, a gene that is involved in apoptosis in schizophrenia." (PMID 27028512, 2016). "In a study based on the dataset of the Stanley Neuropathology Consortium, comparing gene expression in bipolar disorder and schizophrenia versus controls, TNFSF10 had a significant contribution to the support vector machine algorithm for classification of schizophrenia or bipolar versus controls.." (PMID 27028512, 2016).
Sjögren’s Syndrome (2 papers, 2023). "It has been found that TNFSF10 was demonstrated to be upregulated in B cells in primary Sjögren’s syndrome, suggesting a regulatory role for TNFSF10 in B cells." (PMID 37745699, 2023).
vitiligo (2 papers, 2014 to 2022). Generalized well circumscribed patches of leukoderma that are generally distributed over symmetric body locations and is due to autoimmune destruction of melanocytes. "A positive correlation between TNFSF10 and macrophage abundance has actually been found in vitiligo." (PMID 35406685, 2022).
amyloidosis (1 paper, 2025). A disorder characterized by the localized or diffuse accumulation of amyloid protein in various anatomic sites. "Given the concurrent immunological changes and neuropathology observed in 3xTg-AD mice, we investigated whether administering anti-TNFSF10 mAb at a late stage of pathology could modulate amyloidosis in both the hippocampus and spleen of these mice." (PMID 39918606, 2025). "Given that Aβ plaques deposition is a feature typical of AD pathogenesis and progression, and in light of the changes in the immune environment observed both in the brain and the spleen, we investigated whether the anti-TNFSF10 mAb treatment could affect amyloidosis in 3xTg-AD mice." (PMID 39918606, 2025).
autosomal dominant polycystic kidney disease (1 paper, 2021). Autosomal dominant form of polycystic kidney disease. "Conversely, circulating TNFSF10 was decreased in patients with autosomal dominant polycystic kidney disease compared with normal individuals." (PMID 34356656, 2021).
Erythema (1 paper, 2016). Redness of the skin, caused by hyperemia of the capillaries in the lower layers of the skin. "Finally, acute and subacute dermatitis (10 cases), acute erythema (44 cases), acute hyperpigmentation (7 cases), late fibrosis (28 cases), and late telangiectasia (3 cases) were evaluated for association with these three TRAIL/TNFSF10 SNPs." (PMID 26982083, 2016).
ischemic cardiomyopathy (1 paper, 2023). Ischemic cardiomyopathy is a cardiomyopathy in which a weakness in the muscle of the heart due to inadequate oxygen delivery to the myocardium with coronary artery disease being the most common cause. "It was reported that TNFSF10 could be a marker of necroptosis in various diseases, such as ischemic cardiomyopathy and cancers." (PMID 37745699, 2023).
kidney injury (1 paper, 2021). Trauma to the kidney. "Nevertheless, it is not clear how to regulate TNFSF10 through post-transcription of miRNAs, especially in hypoxia-induced kidney injury." (PMID 34356656, 2021).
metastasis (1 paper, 2023). The spread or migration of cancer cells from one part of the body (where they first appeared) to another. "Also, we compared the different expression of TNFSF10 between metastasis tumor and primary tumor." (PMID 37670976, 2023).
premature ovarian failure (1 paper, 2019). "It positively regulates cell apoptosis by targeting the expression of tumor necrosis factor superfamily member 10 (TNFSF10) and fibronectin type III domain containing 1 (FNDC1) in mice with premature ovarian failure." (PMID 30777008, 2019).
uterine disease (1 paper, 2022). "Pregnancy regulated genes downstream of AIRE in cows following uterine infection are all upregulated (EIF2AK2, IFI44, HERC6, PARP14, TNFSF10), suggesting the dysregulated expression of these genes could be important for pregnancy establishment following uterine disease." (PMID 35358206, 2022).